ATP13A3 (ATPase 13A3)
Diseases named in the same sentence as ATP13A3 in open-access papers (continued):
Sharing a sentence is not in itself a finding about the gene and the disease.
neuroblastoma (continued). "We observed that ATP13A3 silencing in both MYCN‐amplified (KELLY) and non‐MYCN‐amplified (SH‐SY5Y) neuroblastoma cells significantly attenuated cell growth and that this was a dose‐dependent effect as less effective silencing was associated with less pronounced effects on growth inhibition." (PMID 39981745, 2025). "In relation to ATP13A3 however, high ATP13A3 expression levels negatively correlate with survival of neuroblastoma patients, irrespective of MYCN status." (PMID 39981745, 2025). "Conversely, in this study in neuroblastoma, we observed in neuroblastoma cells that ATP13A3 knockdown increases sensitivity to DFMO, suggesting that high ATP13A3 expression might drive resistance to DFMO." (PMID 39981745, 2025). "Our data show that ATP13A3 represents an interesting novel therapeutic target to inhibit the polyamine transport system in neuroblastoma to increase the efficacy of DFMO treatment and limit neuroblastoma growth." (PMID 39981745, 2025). "Also, ATP13A3 knockdown appears effective in inhibiting growth in both MYCN‐amplified and non‐MYCN amplified neuroblastoma cell lines." (PMID 39981745, 2025). "In investigating and comparing the potential roles of SLC3A2 and ATP13A3 in polyamine uptake under basal and DFMO‐treated conditions, our work highlights notable similarities and differences in the role of both candidate transporters in neuroblastoma." (PMID 39981745, 2025). "Furthermore, c‐MYC also binds the ATP13A3 and ODC1 promoter in neuroblastoma cells, albeit at a different region than MYCN, potentially denoting differences in MYCN and c‐MYC‐mediated regulation of expression." (PMID 39981745, 2025). "Knockdown of ATP13A3 alone was sufficient to prevent any DFMO‐induced compensatory increase in radiolabeled putrescine and spermidine uptake in both MYCN‐amplified and non‐MYCN amplified neuroblastoma cell lines." (PMID 39981745, 2025). "Our analysis of ChIP‐seq databases of MYCN‐amplified and c‐MYC‐expressing neuroblastoma cells, suggests that both MYCN and c‐MYC can directly bind the promotor of ATP13A3, though each at different regions, and thus may regulate ATP13A3 mRNA levels." (PMID 39981745, 2025). "While it remains unclear whether ATP13A3 levels can be used to predict responsiveness to DFMO, we noted a trend toward an increase in ATP13A3 protein levels in response to DFMO treatment of neuroblastoma cells (data not shown)." (PMID 39981745, 2025). "Moreover, multivariate analysis showed that elevated ATP13A3 expression is an independent predictor of poor prognosis in neuroblastoma, independent of MYCN amplification." (PMID 39981745, 2025). "Here, we report that knockdown of ATPase 13A3 (ATP13A3), a member of the P5B‐ATPase polyamine transporter family, limited basal and DFMO‐induced polyamine uptake, attenuated MYCN‐amplified and non‐MYCN‐amplified neuroblastoma cell growth, and potentiated the inhibitory effects of DFMO." (PMID 39981745, 2025). "In line with our previous results and similar to ATP13A3 silencing, AMXT 1501 effectively blocks putrescine and spermidine uptake and prevents the DFMO‐induced compensatory increase in polyamine uptake in both MYCN‐amplified and non‐MYCN amplified neuroblastoma cells." (PMID 39981745, 2025). "This may reflect the differences in (i) endosomal localization between ATP13A3 (early/recycling endosomes) and ATP13A2 (late endo/lysosomes), (ii) cell type properties (endothelial versus neuroblastoma cells) and/or (iii) relative expression levels of ATP13A3 versus ATP13A2." (PMID 36830711, 2023). "Similarly, while the silencing of either ATP13A3 or SLC3A2 in neuroblastoma cells resulted in reduced polyamine uptake, only the silencing of ATP13A3, and not of SLC3A2, was sufficient to prevent the compensatory increase in polyamine uptake under DFMO treatment." (PMID 39981745, 2025).
neuroblastoma (continued). "Combined, our data demonstrate that ATP13A3 silencing counters the DFMO‐induced upregulation of polyamine uptake, and enhances the efficacy of DFMO, suggesting that ATP13A3 might be a clinically relevant therapeutic target to potentiate polyamine biosynthesis inhibition approaches in neuroblastoma." (PMID 39981745, 2025).
Parkinsonism (3 papers, 2012 to 2024). Characteristic neurologic anomaly resulting from degeneration of dopamine-generating cells in the substantia nigra, a region of the midbrain, characterized clinically by shaking, rigidity, slowness of movement and difficulty with walking and gait. "Mutations in the gene ATP13A3/PARK9 have been recently associated with familial forms of parkinsonism." (PMID 22457822, 2012). "Strikingly, ATP13A2 mutations are not implicated in cardiovascular but in neurodegenerative diseases, such as Parkinson’s disease, indicating that ATP13A2 and ATP13A3 exert distinct (patho) physiological roles." (PMID 33310703, 2021).
breast carcinoma (2 papers, 2023 to 2026). "Notably, ATP13A3 emerges as a previously unrecognized adverse prognostic marker, particularly in basal-like breast cancer, where its expression associates with proliferative and oncogenic signaling programs." (PMID 41750325, 2026). "Follow-up studies are required to investigate whether increased ATP13A4 expression is a general hallmark of breast cancer, or whether other polyamine transporters such as ATP13A2 and ATP13A3 may also be implicated." (PMID 37371498, 2023).
endothelial dysfunction (2 papers, 2022 to 2024). In vascular diseases, endothelial dysfunction is a systemic pathological state of the endothelium (the inner lining of blood vessels) and can be broadly defined as an imbalance between vasodilating and vasoconstricting substances produced by (or acting on) the endothelium. "ATP13A3 deficiency impairs polyamine homeostasis and uptakes and drives endothelial dysfunction." (PMID 38626311, 2024).
pulmonary hypertension (2 papers, 2019 to 2023). Increased pressure within the pulmonary circulation due to lung or heart disorder. "Hence, the Tibetan-enriched mutations of ATP13A3 may protect Tibetans from pulmonary hypertension (PAH)." (PMID 37055782, 2023).
atrial septal defect (1 paper, 2022). Interauricular communication is a congenital malformation characterized by a communication between the atrial chambers of the heart. "Subsequent WES analysis in a paediatric cohort detected a novel ATP13A3 missense variant in a child with PAH and atrial septal defect (ASD)." (PMID 35772304, 2022).
channelopathy (1 paper, 2022). Channelopathies are a group of diseases caused by the dysfunction of ion channel subunits or their interacting proteins. "Roles of genetic variants in three channelopathy genes—ABCC8, ATP13A3, and KCNK3—have been validated in multiple independent studies, and explain ~2.7% of PAH cases." (PMID 35204766, 2022).
COVID-19 (1 paper, 2021). A disease caused by infection with severe acute respiratory syndrome coronavirus 2. "Plasma cells also expressed higher levels of the OXPHOS gene ATP13A3 in COVID-19 patients, which was positively associated with antibody secretion and survival of PCs." (PMID 33936072, 2021).
head and neck squamous cell carcinoma (1 paper, 2024). A squamous cell carcinoma that arises from any of the following anatomic sites: lip and oral cavity, nasal cavity, paranasal sinuses, pharynx, larynx, and salivary glands. "notice that ATP13A3 is overexpressed in head and neck squamous cell carcinoma, which is consistent with the present study findings." (PMID 38722543, 2024).
Onset (1 paper, 2022). The age group in which disease manifestations appear. "Identification of biallelic ATP13A3 variants in three families with severe cPAH, in conjunction with recently identified monoallelic variants in adult-onset PAH, indicates semidominant inheritance for the ATP13A3 gene." (PMID 34493544, 2022).
serous ovarian tumors (1 paper, 2008). "For example, TMEM158, HEG1, PLOD2 and ATP13A3, were recently found differentially expressed greater than 3-fold in a comparative analysis of primary cultures of normal ovarian surface epithelial cells and malignant serous ovarian tumors." (PMID 18687136, 2008).
cancer (8 papers, 2008 to 2025). A tumor composed of atypical neoplastic, often pleomorphic cells that invade other tissues. "Highly metastatic cancer cells with high polyamine import express higher levels of the full-length ATP13A3 compared to cells with slow proliferation and low import activity." (PMID 35260637, 2022). "Highly metastatic cancer cells expressing high levels of the full-length ATP13A3 protein are sensitive to polyamine targeted therapies and respond to polyamine stimuli by altering the cellular localization of ATP13A3." (PMID 35260637, 2022). "Proteomic data showed that ARG1, ATP13A3, and SRM were highly expressed in cancer tissues, whereas PAOX and SMS had low expression." (PMID 36505496, 2022). "Importantly, our model provides a connection between cancer metabolic commitments and immune evasion and provides clearly defined targets for drug development (ODC, CAV1-mediated endocytosis, ATP13A3)." (PMID 34945011, 2021). "In cells, ATP13A3‐mediated polyamine uptake can be prevented by AMXT 1501, a polyamine uptake inhibitor currently in phase I/II clinical trials for cancer, indicating that preventing polyamine uptake via ATP13A3 may at least partially explain the mode of action of the drug." (PMID 39981745, 2025).
tumor (5 papers, 2013 to 2025). "The epithelial (tumor) portion of the PDAC samples showed an increase in the expression of ATP13A3 (polyamine import) and SLC3A2 (diamine exporter) and lower expression of CAV1." (PMID 34945011, 2021). "This is of particular importance as AMXT 1501, being a polyamine analog, may also target other polyamine transporters alongside ATP13A3, and may be subjected to polyamine competition in the tumor environment." (PMID 39981745, 2025). "Functional rescue experiments mentioned that the pro-tumor effect of pcDNA 3.1-RMRP on proliferation, apoptosis, and glycolysis as above tested could be prevented after knocking down ATP13A3." (PMID 38722543, 2024).
ATP13A3 also shares sentences with these, for which no sentence is quoted: melanoma (2 papers); acute myeloid leukemia (1); cervical cancer (1); Childhood onset (1); colon cancer (1); colorectal cancer (1); esophageal squamous cell carcinoma (1); hepatocellular carcinoma (1); heritable pulmonary arterial hypertension (1); Hypertension (1); Kufor-Rakeb syndrome (1); neurodegenerative disease (1); non-small cell lung carcinoma (1); ovarian carcinoma (1); pulmonary veno-occlusive disease (1).